LINC01478 (long independently transcribed non-coding RNA 1478)
Synonyms: LOC124904290
Gene: Long non-coding RNA gene on chromosome 18 (44,280,768 to 44,579,978, reverse strand). Ensembl gene ENSG00000267337.
Diseases named in the same sentence as LINC01478 in open-access papers:
LINC01478 is named in the same sentence as 2 diseases in open-access papers, as found by Europe PMC text mining. Sharing a sentence is not in itself a finding about the gene and the disease. The quoted sentences say what the papers report.
cancer (1 paper, 2024). A tumor composed of atypical neoplastic, often pleomorphic cells that invade other tissues. "The more cancer-specific lincRNAs are LINC00470, LINC00668, LINC00907, LINC01254, LINC01415, LINC01478, and LINC01539." (PMID 38540157, 2024).
LINC01478 also shares sentences with these, for which no sentence is quoted: testicular germ cell tumor (1 paper).